RAC1 (Rac family small GTPase 1)
Diseases named in the same sentence as RAC1 in open-access papers (continued):
Sharing a sentence is not in itself a finding about the gene and the disease.
thyroid cancer (14 papers, 2014 to 2025). "MEG3 inhibits migration and invasion of thyroid cancer cells by acting on Rac1 and is linked with lymph node metastasis." (PMID 32596158, 2020). "A previous study reported that the variation of RAC1 may lead to acquired resistance to dabrafenib in patients with thyroid cancer and is associated with the process of dedifferentiation." (PMID 38463514, 2024). "This study showed that the Rac1 gene is negatively regulated by MEG3 at the posttranscriptional level in thyroid cancer." (PMID 32596158, 2020). "In the current study, we showed that Tiam1/Rac1 signaling was regulated by Pard3 in thyroid carcinomas." (PMID 30171257, 2019). "Thyroid carcinoma tissues contain Tiam1, which is a Rac1-specific GEF that is overexpressed in thyroid carcinomas." (PMID 30171257, 2019). "Our findings showed that miR-483 upregulated Tiam1/Rac1 signaling in thyroid carcinomas, possibly by downregulating Pard3." (PMID 30171257, 2019). "In previous studies, the role of miRNA-101 (miR-101) in tumors has been identified as a tumor suppressor and, until now, the role of miR-101 and Rac1 in thyroid cancer has remained undefined." (PMID 25202416, 2014). "The expression of Rac1 was also observed to inversely correlate with miR-101 expression in PTC tissues; knockdown of Rac1 by shRNA inhibited thyroid cancer cell migration and invasion, resembling that of miR-101 overexpression." (PMID 25202416, 2014). "This suggests that RAC1 may play a significant role in thyroid cancer, particularly in terms of drug resistance and cellular differentiation." (PMID 38463514, 2024). "Notably, the lncRNA MEG3 antagonizes RAC1 expression in thyroid carcinoma by interacting with its 3’-UTR mRNA to function as a RAC1 tumor inhibitor." (PMID 38745221, 2024). "Besides RAC1 tumor cells from pancreatic, breast, colon, lung, and thyroid cancers express an alternatively spliced isoform of the human RAC1 gene, designated RAC1b, that differs from RAC1 by the inclusion of an additional exon." (PMID 34771704, 2021). "The migration and invasion of thyroid cancer cells may be influenced by miR-483, in a mechanism involving regulation of Pard3 expression and Tiam/Rac1 signaling." (PMID 30171257, 2019). "Overall, the results of the present study have shown that Pard3 inhibited TGF-β1-induced cell EMT and invasion, concomitant with miR-483 downregulating Pard3 in thyroid carcinoma cells, to activate Tiam/Rac1 signaling and promoting EMT, as well as cell migration and invasion." (PMID 30171257, 2019). "Furthermore, miR-101 inhibits the invasion and migration in thyroid cancer cells; miR-101 directly inhibited Rac1 expression by targeting its 3′UTR." (PMID 25202416, 2014). "In addition, Rac1 was downregulated and found to inversely correlate with miR-101 levels in thyroid carcinoma." (PMID 25202416, 2014). "Thus, we hypothesized that it might be possible to improve the response of BRAF V600E-positive thyroid cancer cells to MEK inhibitors by increasing RAC1 activity." (PMID 34831012, 2021). "An inverse correlation between MEG3 and Rac1 was observed, supporting the role of MEG3 as a tumor suppressor in thyroid carcinoma." (PMID 41150811, 2025). "This is particularly true for the RAC1/PAK1 pathway, TWIST1 and EGFR1 proteins, which are known drivers of proliferation and EMT in aggressive thyroid cancer cells." (PMID 34638434, 2021). "Consistently, our findings revealed that in a thyroid carcinoma cell model with BRAF V600E genetic background, the upregulation of RAC1 activity is able to potentiate the positive impact on NIS expression induced by MEK inhibition." (PMID 34831012, 2021). "Using proteomics, we previously characterized an intracellular signaling pathway derived from SRC kinase that acts through the small GTPase RAC1 to recruit and bind the actin-anchoring adaptor EZRIN to NIS, regulating its retention at the PM of both non-transformed and cancer thyroid cells." (PMID 36358781, 2022).
autism (13 papers, 2013 to 2025). Persistent deficits in social interaction and communication and interaction as well as a markedly restricted repertoire of activity and interest as well as repetitive patterns of behavior. "The inhibition of Rac1 activity induces social interaction deficits in wild-type mice, whereas activating Rac1 can rescue autism-like defects in Shank3-deficient mice (ASD model)." (PMID 37445914, 2023). "Some of these autism-risk genes were recently found to be linked to ASD via the Rac1-associated signaling network in the brain." (PMID 33299404, 2020). "Rac1 and Fmr1, which regulate Retro-I in Drosophila, are high-risk genes for autism." (PMID 36897069, 2023). "In a recent study with fruit flies (Drosophila melanogaster), Rac1 was a functional converging point for multiple autism risk genes, including Fragile X mental retardation 1 (FMR1), UBE3A, Neurexin-1 (Nrx-1), Neuroligin-4 (Nlg4), and Tuberous sclerosis complex 1 (TSC1)." (PMID 33299404, 2020). "Hence, the two autism/dyslexia-linked mutants of Dock4 showed impaired abilities on activation of both Rac1 and Rap1." (PMID 32009906, 2019). "Indeed, it has been demonstrated that Rac1 activation is defective in multiple autism-related gene mutations, including the dnrx gene, and that Rac1 has been proposed to be a converging node linked to ASD." (PMID 28710284, 2017). "Dock4 deficiency causes a marked reduction in hippocampal Rac1 activity, while hippocampal Rac1 replenishment in the Dock4 KO mice reverses autism-like social impairments in these mice." (PMID 37445914, 2023). "A computational network model for gene–environment interactions (GENVI model) in the ASD context showed that Rac1 has a strong etiological relevance in autism-related neuropathological events." (PMID 37445914, 2023). "Of note, multiple autism risk genes, such as UBE3A, functionally converge on RAC1 and RAC1-dependent memory impairment is implicated in determining the behavioral inflexibility underlying the impaired reversal learning in autistic patients." (PMID 34943902, 2021). "Supporting this notion, restoration of normal activity of Rac1 or its downstream effectors was demonstrated as a successful approach for correcting autism-like behaviors and synaptic abnormalities." (PMID 31388105, 2021). "In the vermis of adult subjects with autism, RAC1 was significantly increased while APP 120, STEP 66 kDa, STEP 27 kDa, and homer 1 were significantly decreased when compared with healthy controls." (PMID 23803181, 2013). "In BA9 of adults with autism we observed significantly increased ratios for RAC1/β-actin (P <0.031, d = 1.32), RAC1/NSE (P <0.042, d = 1.24) and significantly reduced ratios for homer 1/β-actin (P <0.027, d = −1.37), homer 1/NSE (P <0.020, d = −1.43)." (PMID 23803181, 2013). "In BA9 of adults with autism there were significant increases in RAC1 and STEP 46 kDa and a significant decrease in homer 1 vs. controls." (PMID 23803181, 2013). "In the cerebellar vermis of adults with autism we observed significantly increased expression of the RAC1/β-actin ratio (P <0.025, d = 1.62) and the RAC1/NSE ratio (P <0.016, d = 1.73)." (PMID 23803181, 2013). "Moreover, ArgGAP32 (a GAP for Rho GTPase), P-Rex1 (a specific GEF for Rac1), the GEF1 domain of Trio, and PAK, are also associated with autism-like social behavior in ASD patients and rodent models." (PMID 37445914, 2023). "To study whether the autism/dyslexia-linked variations of DOCK4 have influences on its Rac1 GEF activity, we compared the abilities of Rac1 activation by Dock4-945VS and R853H with that of the wild-type (WT) protein when exogenously expressed in cells." (PMID 32009906, 2019). "Fragile X syndrome, the most common inherited form of Autism, may also stem from synaptic Rac1 dysregulation." (PMID 30042656, 2018).
autism (continued). "It is tempting to speculate that RAC1 overexpression in autism may also be responsible for increased glial fibrillary acidic protein (GFAP) immunoreactivity detected in the brains of subjects with autism." (PMID 23803181, 2013). "Higher levels of RAC1 in Caucasian adults with autism compared to African American adults with autism is a novel finding that requires further investigation, and it may be due to genetic or epigenetic factors." (PMID 23803181, 2013). "The altered expression of proteins that may contribute to altered dendritic protein translation (homer 1), altered dendritic morphology (APP and RAC1), and receptor subunit expression (STEP), potentially contribute to the cognitive and behavioral impairments associated with autism and FXS." (PMID 23803181, 2013). "One of the autism candidate genes, AUTS2 is involved in neuritogenesis via Rac1 signaling activation in the developing brain." (PMID 34260616, 2021). "Taken together, the results of current postmortem studies provide novel evidence that targets of FMRP and mGluR5 signaling (RAC1, homer 1, APP, and STEP) display altered expression in the cerebellar vermis and BA9 of people with autism." (PMID 23803181, 2013). "There were significant increases in RAC1, APP 120 kDa and APP 80 kDa proteins in BA9 of children with autism vs. healthy controls." (PMID 23803181, 2013). "Lack of FMRP in FXS (and in some individuals with autism), would also favor PIKE activation of mTOR and downstream Rho GTPases including Rac1 and cofilin that in turn would cause actin disassembly and myelination." (PMID 31024350, 2019).
Cognitive impairment (13 papers, 2010 to 2025). Abnormal cognition is characterized by deficits in thinking, reasoning, or remembering. "In mice loss of ArhGAP15 results in increased Rac1/Rac3 activity, reduced spine density, reduced axonal and dendritic complexity and cognitive deficits." (PMID 29925821, 2018). "Thus, Rac1 activation and function are becoming an important therapeutic target to rescue disorders associated with cognitive impairment." (PMID 37078409, 2023). "Thus we conclude that both hyper- and hypoactivation of Rac1/Rac3 have similar consequences on migration, neuritogenesis and synaptogenesis, and impacts on the maturation of the inhibitory network causing similar cognitive deficits." (PMID 27713499, 2016). "The studies included in this research similarly corroborate that acupuncture increases miR-132 expression, decreases p250GAP, and upregulates Rac1 expression, thereby improving cognitive function in a sleep disorder-induced cognitive impairment model." (PMID 40177248, 2025). "Downstream of Rac1, defects in the activity and localization of the p21-activated kinases (PAKs) have been observed in transgenic AD mouse models and resulted in cognitive impairments and dendritic spine alterations." (PMID 38799759, 2024). "Like SigmaR1, IQGAP1 promotes ROS via Rac1 GTPase, and studies in mouse models have implicated IQGAP1 in memory and cognitive deficits." (PMID 37444574, 2023). "Moreover, our study highlights not only the role of Rac1 in drug reward memory but also the role of the NAc in drug-induced cognitive impairments." (PMID 31660086, 2019). "However, the precise intracellular mechanisms underlying the effects of Rac1 on METH-associated contextual memory and cognitive impairments remain to be elucidated." (PMID 31660086, 2019). "Conditional deletion of Rac1 results in mice with greater hyperactivity and cognitive impairment compared to mice with the deletion of Rac3, leading to more evident alteration of both the morphological and physiological properties of the inhibitory circuits in the Rac1 mutants." (PMID 31514269, 2019). "Importantly, the degree of the alteration in the circulating Rac1 pool reflected the severity of the cognitive impairment, suggesting a potential role of Rac1 as a biomarker for AD." (PMID 30005699, 2018). "Thus, to develop novel therapies for rescuing cognitive impairment, a reasonable approach might be to target Rac1 or its direct regulators." (PMID 29925821, 2018). "Inhibition of ischemia-induced Rac1 activation reduces NADPH oxidase activation and superoxide production in hippocampal CA1 in vivo, with consequent reductions in neuronal damage and cognitive impairment." (PMID 29046349, 2017). "We also evaluated Rac1 protein levels in the plasma of 114 patients affected by AD, 47 subjects with mild cognitive impairment (MCI), and 102 sex and age-matched non-demented controls." (PMID 30005699, 2018). "Indeed, inhibition of ischemia-induced Rac1 activation reduces NADPH oxidase activation and superoxide production in hippocampal CA1 in vivo, with consequent reductions in neuronal damage and cognitive impairment." (PMID 29046349, 2017).
diabetic nephropathy (13 papers, 2016 to 2024). "However, the rs836478-C/T-T/T genotypes of RAC1 were found to be associated with an increased risk of diabetic nephropathy in male diabetics (OR 1.84, 95% CI 1.06–3.19, p = 0.024) in the dominant model." (PMID 36979960, 2023). "Activation of Ras-related C3 botulinum toxin substrate 1 (Rac1) has been implicated in diverse kidney diseases, yet its in vivo significance in diabetic nephropathy (DN) is largely unknown." (PMID 29497040, 2018). "There have been no studies on humans or animals that have investigated the expression level of the RAC1 gene in diabetic nephropathy, but there are studies that have investigated other NOX enzymes." (PMID 36979960, 2023). "Overactivation of Rac-1 has been shown as the corpus of podocytes FP effacement in human diabetic nephropathy, hypertensive kidney disease and nephrotic syndrome." (PMID 31040292, 2019). "A haplotype analysis revealed that none of the RAC1 haplotypes were associated with diabetic nephropathy." (PMID 36979960, 2023). "Finally, Ying and co-workers have recently observed that the binding of RAC1 to the pyrin domain containing 3 (NLRP3) activates the NLRP3 inflammasome in the kidney and accelerates the pathological processes underlying diabetic nephropathy." (PMID 36979960, 2023). "Ras-related C3 botulinum toxin substrate 1 (RAC1) activation plays a vital role in diabetic nephropathy (DN), but the exact mechanism remains unclear." (PMID 34194338, 2021). "A late clinical trial TRACTION-2 using GFB-887, a podocyte targeted small molecule TRPC5 inhibitor, to treat diabetic kidney disease was designed based on previous in vitro and in vivo studies showing a protective effect of TRPC5 inhibition via the Rac1 signaling pathway." (PMID 35387335, 2022).
diabetic retinopathy (13 papers, 2015 to 2023). "The sexual dimorphism of the associations between the RAC1 gene polymorphisms and the risk of diabetic retinopathy, particularly in men, appears to be due to the male sex itself being a known risk factor for this complication." (PMID 36979960, 2023). "The present study found, for the first time, that the polymorphisms of the gene encoding Rac family small GTPase 1 (RAC1) in type 2 diabetes are associated with complications such as diabetic retinopathy, neuropathy, and angiopathy of the lower extremities." (PMID 36979960, 2023). "In diabetic retinopathy, both prenylation and palmitoylation are implicated in Rac1 activation, and inhibition of prenylation impedes glucose-induced Rac1-Vav2 association and Nox2 activation-mitochondrial damage, preventing capillary cell apoptosis." (PMID 34063353, 2021). "The same G-protein can also be modulated by multiple GEFs, and Vav2 is considered as another important GEF for Rac1 activation; our recent work has implicated Vav2 in the activation of Rac1-Nox2 signaling in diabetic retinopathy." (PMID 31277234, 2019). "Furthermore, the polymorphism rs836478 of RAC1 was linked to diabetic retinopathy and nephropathy in males, whereas the polymorphism rs10238136 was linked to diabetic angiopathy in females." (PMID 36979960, 2023). "Oxidative stress plays a significant role in the development of diabetic retinopathy, and increase in cytosolic ROS, produced by the activation of Rac1–Nox2, is an early event, which damages the mitochondria, accelerating loss of capillary cells." (PMID 36202842, 2022). "Rac1–Nox2–ROS activation is an early event in the pathogenesis of diabetic retinopathy, and is seen before mitochondrial damage or capillary cell loss." (PMID 36202842, 2022). "In the development of diabetic retinopathy, activation of Rac1–Nox2–ROS signaling precedes mitochondrial damage-capillary cell apoptosis; the effect of regulation of inhibition of SPT on mitochondrial damage and cell death was evaluated." (PMID 36202842, 2022). "This study aims to investigate the effect of inhibition of SPT on Rac1 activation in diabetic retinopathy." (PMID 36202842, 2022). "Our aim was to investigate the effect of inhibition of the rate limiting enzyme of the de novo ceramide biosynthesis, serine palmitoyl-transferase (SPT), on Rac1 activation in diabetic retinopathy." (PMID 36202842, 2022). "In the pathogenesis of diabetic retinopathy production of ROS by Rac1–Nox2 activation is an early event, and this ROS production in the cytosol precedes mitochondrial damage, further exacerbating accumulation of free radicals." (PMID 36202842, 2022). "Moreover, addition of hyperlipidemia in a hyperglycemic milieu (type 2 diabetes) further exacerbates Rac1-Nox2-ROS activation, and with time, this accelerates and worsens the mitochondrial damage, ultimately leading to the accelerated capillary cell loss and the development of diabetic retinopathy." (PMID 34063353, 2021). "Activation of Rac1-Nox2 is an early event in the pathogenies of diabetic retinopathy, and sustained activation of Rac1-Nox2-ROS damages the mitochondria, initiating a self-propagating a vicious cycle of free radicals." (PMID 34063353, 2021). "Activation of Rac1 is an early event in the pathogenies of diabetic retinopathy, and sustained activation of Rac1-Nox2-ROS damages the mitochondria, initiating a self-propagating a vicious cycle of free radicals." (PMID 34238980, 2021). "This makes targeting Rac1 Nox2 signaling an attractive therapeutic option to prevent the development and progression of diabetic retinopathy." (PMID 34063353, 2021). "Epigenetic modifications play a major role in its transcriptional activation of Rac1 in the pathogenesis of diabetic retinopathy, and since epigenetic modifications can also be reversed, targeting such modifications is another possible therapeutic option." (PMID 34063353, 2021).